SLC27A1 (solute carrier family 27 member 1)
Description:
Mediates the import of long-chain fatty acids (LCFA) into the cell by facilitating their transport at the plasma membrane. Also functions as an acyl-CoA ligase catalyzing the ATP-dependent formation of fatty acyl-CoA using LCFA and very-long-chain fatty acids (VLCFA) as substrates, which prevents fatty acid efflux from cells and might drive more fatty acid uptake. May act directly as a bona fide transporter, or alternatively, in a cytoplasmic or membrane-associated multimeric protein complex to trap and draw fatty acids towards accumulation. Plays a pivotal role in regulating available LCFA substrates from exogenous sources in tissues undergoing high levels of beta-oxidation or triglyceride synthesis. May be involved in regulation of cholesterol metabolism (By similarity). Probably involved in fatty acid transport across the blood barrier.
Synonyms: FATP-1; ACSVL5; FATP1; FATP; MGC71751; FLJ00336
Tractability: Small molecule: a high-quality ligand is known; it belongs to a druggable protein family. Antibody: its Gene Ontology location is reachable by antibodies, with high confidence; UniProt places it where antibodies can reach, with medium confidence; UniProt predicts a signal peptide or a membrane-spanning region; the Human Protein Atlas places it where antibodies can reach. PROTAC: ubiquitination databases record sites on it; its protein half-life has been measured; a small molecule that binds it is known.
Target class: Electrochemical transporter; Transporter; SLC27 family of fatty acid transporters; SLC superfamily of solute carriers
Gene: Protein-coding gene on chromosome 19 (17,467,666 to 17,506,190, forward strand). Ensembl gene ENSG00000130304.
Subcellular location: Cell membrane; Endomembrane system; Cytoplasm
Subcellular location (Human Protein Atlas): Plasma membrane; Cytosol; Mitochondria
Pathways (Reactome):
Metabolism: Arachidonate metabolism; PPARA activates gene expression
Transport of small molecules: Transport of fatty acids
Gene Ontology:
Molecular function: biotin transmembrane transporter activity; efflux transmembrane transporter activity; long-chain fatty acid transmembrane transporter activity; protein binding; fatty acid transmembrane transporter activity; long-chain fatty acid-CoA ligase activity; oleoyl-CoA ligase activity; arachidonate-CoA ligase activity; identical protein binding; protein serine/threonine kinase activator activity; very long-chain fatty acid-CoA ligase activity
Biological process: biotin import across plasma membrane; biotin transport; export across plasma membrane; lipid transport across blood-brain barrier; long-chain fatty acid import across plasma membrane; long-chain fatty acid import into cell; long-chain fatty acid transport; glucose import in response to insulin stimulus; long-chain fatty acid metabolic process; medium-chain fatty acid transport; positive regulation of triglyceride biosynthetic process; transport across blood-brain barrier
Cellular component: membrane; plasma membrane; basal plasma membrane; endoplasmic reticulum; endoplasmic reticulum membrane; cytoplasm; endomembrane system
Genetic constraint (gnomAD): Loss-of-function variants: 63 observed, 59.72 expected, observed/expected ratio (o/e) 1.05, 90% interval 0.86 to 1.3. The upper end of that interval is the gene's LOEUF score, 1.3, which puts it in group 5 of 6, group 1 being the genes least tolerant of losing a copy. Missense variants: 903 observed, 908.5 expected, observed/expected ratio (o/e) 0.99, 90% interval 0.94 to 1.05. Synonymous variants: 435 observed, 392.08 expected, observed/expected ratio (o/e) 1.11, 90% interval 1.02 to 1.2.
Homologues: Orthologues: chimpanzee SLC27A1 (99% identical), macaque SLC27A1 (97% identical), dog SLC27A1 (93% identical), rat Slc27a1 (90% identical), mouse Slc27a1 (89% identical), pig SLC27A1 (83% identical), guinea pig SLC27A1 (79% identical), zebrafish slc27a1a (66% identical), zebrafish slc27a1b (63% identical), Drosophila melanogaster Fatp2 (46% identical), Drosophila melanogaster Fatp1 (44% identical), Caenorhabditis elegans acs-20 (42% identical), and 21 more. Paralogues in human: SLC27A4 (62% identical), SLC27A2 (38% identical), SLC27A3 (37% identical), SLC27A5 (37% identical), SLC27A6 (35% identical), ACSL1 (19% identical), ACSL6 (18% identical), ACSL3 (18% identical), ACSL4 (17% identical), ACSL5 (17% identical), ACSBG2 (16% identical), ACSBG1 (15% identical).
Diseases named in the same sentence as SLC27A1 in open-access papers:
SLC27A1 is named in the same sentence as 58 diseases in open-access papers, as found by Europe PMC text mining. Sharing a sentence is not in itself a finding about the gene and the disease. The quoted sentences say what the papers report.
melanoma (32 papers, 2019 to 2025). A malignant, usually aggressive tumor composed of atypical, neoplastic melanocytes. "The SLC27 family, such as SLC27A1 (FATP1) in melanoma, stimulates fatty acid uptake/metabolism, enhancing invasiveness." (PMID 41425581, 2025). "have proved that in transgenic zebrafish and xenograft mice, melanoma cells adjacent to stromal adipocytes can intake adipocyte-derived lipid through the overexpressed fatty acid transport protein 1 (FATP1/SLC27A1) lipid transporter." (PMID 36003368, 2022). "LPL, CD36, FATP1 (SLC27A1), and FATP2 (SLC27A2), implicated in increased FA uptake into melanoma cells, are unaffected by point mutation in cancer and display gene amplification in 2%–8% of cases." (PMID 35732120, 2022). "FATP1 (SLC27A1) accelerates melanoma initiation, and FATP2 (SLC27A2) confers melanoma resistance to BRAF and MEK inhibition by promoting FA uptake from the microenvironment." (PMID 35764645, 2022). "In this regard, the participation of a different FA transporter, FATP1/SLC27A1, has also been shown to be crucial for melanoma progression and dissemination." (PMID 35912100, 2022). "SLC27A1 is rarely studied in tumors, but in recent years, some articles have pointed out that SLC27A1 is highly expressed in melanoma and breast cancer and enhances tumor invasion, migration, and growth." (PMID 36105089, 2022). "Melanoma cells overexpress FATP1/SLC27A1 that, in transgenic zebrafish experimental model, work together with BRAFV600E in sustaining CM development." (PMID 32528879, 2020). "For instance, fatty acid metabolism is engaged in melanoma and ovarian tumors, so these tumors could benefit from the inhibition of the fatty acid transport proteins SLC27A1 (also called FATP1) and CD36, respectively." (PMID 33413697, 2021). "For instance, it was recently found that fatty acids derived from adipocytes could be transferred to melanoma cells through the fatty acid transporter protein SLC27A1." (PMID 31921669, 2019). "A study by Zhang and colleagues has also shown that another member of the SLC27A family, SLC27A1 also known as FATP1, could be induced by adipocytes in melanoma cells, allowing them to take up lipids from those adipocytes and become more metastatic." (PMID 39007351, 2024). "Melanomas significantly overexpress FATP1/SLC27A1, one of the six members of the FATP/SLC27A family, and this Melanocyte-specific FATP1 expression works in conjunction with BRAFV600E in transgenic zebrafish to hasten the development of melanoma, an effect also observed in mouse xenograft studies." (PMID 36675128, 2023).
Obesity (31 papers, 2007 to 2025). Accumulation of substantial excess body fat. "Studies have shown that after the knockout of the SLC27A1 gene in mice, the fatty acid uptake in the adipocytes decreases significantly; thus, it can control diet-induced obesity and insulin resistance." (PMID 35603729, 2022). "KEGG pathway analysis showed that two DEmRNAs, Slc27a1 and Slc2a4, were involved in the insulin resistance signaling pathway, which is closely related to obesity (Yu, Kim & Lee, 2017)." (PMID 30842902, 2019). "On the other hand, in a rat model of diet-induced obesity that is associated with IUGR, mRNA and protein levels of CD36, Slc27a1/Fatp1 and Slc27a4/Fatp4 were reported as decreased relative to control." (PMID 31774824, 2019). "scWAT gene expression of SLC27A2, CNR1, DAGLA, MGLL, FAAH, SLC27A1 and SLC27A2 were lower in individuals living with healthy obesity." (PMID 38024342, 2023). "Accordingly, PLA2G2A and PLA2G4A genes were up-regulated by omega-3 polyunsaturated fatty acids supplementation, whereas SLC27A2, CNR1, DAGLA, MGLL, FAAH, SLC27A1, and SLC27A2 genes were found to be down-regulated in people living with healthy obesity." (PMID 38024342, 2023). "Additional evidences of lipid metabolism impairment in overweight and obesity, which are mirrored in PBMC, are provided by a lower expression of SCD1 and SLC27A1 in samples from the OW-OB group observed when analysing a subset of the whole cohort." (PMID 34526523, 2021). "UCP1, PPARG coactivator 1 alpha (PPARGC1A), transcription factor A, mitochondrial (TFAM), T-box transcription factor 1 (TBX1), and solute carrier family 27 member 1 (SLC27A1) expression was assayed in SAT and VAT samples, obtained during sleeve gastrectomy from 62 patients with obesity." (PMID 31440209, 2019). "In human studies, links between both SLC27A1 and SLC27A4, and obesity and T2D have been proposed." (PMID 25784953, 2015).
breast carcinoma (13 papers, 2019 to 2025). "Studies on breast cancer have shown that estrogen receptor-β (ER-β) increases the expression of SLC27A1." (PMID 37239243, 2023). "For instance, SLC27A1 has recently been reported to be highly expressed in breast cancer and may contribute toward an innovative therapeutic strategy." (PMID 34854499, 2022). "Breast cancer cells (BCCs) exposed to CAFs-conditioned media increased their lipid uptake and the expression of FATP1/SLC27A1 (FA transport protein 1), promoting FA transfer." (PMID 31575907, 2019). "FA and estrogen stimulate the expression of FATP1/SLC27A1 (solute carrier family 27 member 1) in TNBC, and FATP1/SLC27A1 expression is higher in the more aggressive MDA-MB-231 cell line, suggesting that active uptake of FAs plays an important role in breast cancer progression." (PMID 40256431, 2025).
Insulin resistance (12 papers, 2014 to 2024). Increased resistance towards insulin, that is, diminished effectiveness of insulin in reducing blood glucose levels. "In the context of humans, mutations within the FATP1/SLC27A1 gene have been firmly linked to metabolic disorders, such as insulin resistance and type 2 diabetes, stemming from compromised cellular fatty acid uptake and utilization." (PMID 38002353, 2023). "Briefly, both BNIP3 and SLC27A1 have been strongly associated with insulin resistance phenotypes." (PMID 33362275, 2020). "For example, SLC27A1 is an insulin-sensitive fatty acid transporter and abnormal SLC27A1 expression may lead to insulin resistance." (PMID 39063189, 2024). "The DEGs Slc27a1, Cpt1a, Srebf1, and Foxo1 were enriched in insulin resistance pathway and also appeared in the network of top 10 upregulated and downregulated mRNAs, indicating these four mRNAs might play key roles in the development of hyperglycemia and T2D in GK rats at the age of 3 and 4 weeks." (PMID 32095365, 2020).
steatosis (10 papers, 2015 to 2025). Increased lipid within the cytoplasm of cells. "Interestingly, the expression of liver fatty acid transport-related genes, including SLC27A4, ACBD3 and SLC27A1, were significantly reduced in FFA induced steatosis cells or HFD induced steatotic liver compared with control groups." (PMID 26330104, 2015).
diabetes (5 papers, 2009 to 2019). "Mice with cardiac-specific overexpression of FATP1 (Slc27a1; ACSVL4) at around 3 months of age developed lipotoxic cardiomyopathy and other pathologic features seen in diabetes." (PMID 23936004, 2013).
Hyperglycemia (3 papers, 2019 to 2023). An increased concentration of glucose in the blood. "Previous studies reported a noncanonical function of phosphor-EPRS1 in activating long-chain fatty acid uptake by binding to SLC27A1 (fatty acid transport protein 1, FATP1) under hyperglycemia stress." (PMID 38201239, 2023).
endometrial carcinoma (2 papers, 2023 to 2024). A malignant tumor arising from the epithelium that lines the cavity of the uterine body. "CD36 and SLC27A1 expression was examined in uterine fibroids and endometrial carcinomas of women." (PMID 39456882, 2024).
Hyperinsulinemia (2 papers, 2019 to 2020). An increased concentration of insulin in the blood. "HFD feeding often results in hyperinsulinemia, and BS1 covers a cis-acting element (between −1347 and −1353) reported to mediate the negative effects of insulin on Slc27a1 gene transcription in adipocytes." (PMID 32059412, 2020).
lymphoma (2 papers, 2019 to 2022). A malignant (clonal) proliferation of B- lymphocytes or T- lymphocytes which involves the lymph nodes, bone marrow and/or extranodal sites. "Thus, the downregulation of Glut-1 and the upregulation of the fatty acid transporter SLC27A1 in DLBCL indicate a shift from a glycolytic to an oxidative metabolism during lymphoma progression." (PMID 31197180, 2019). "Although further functional studies must be conducted to confirm the therapeutic potential of the fatty acid oxidative pathway in aggressive lymphomas, SLC27A1, and the OxPhos pathway, might constitute a promising therapeutic target." (PMID 31197180, 2019).
Melkersson-Rosenthal syndrome (2 papers, 2020 to 2023). The Melkersson-Rosenthal syndrome is a rare disorder characterized by a triad of recurrent orofacial swelling, relapsing facial paralysis and fissured tongue and onset in childhood or early adolescence. "Slc27a1−/− mice do not exhibit skin phenotypes, and a loss-of-function mutation in humans linked to Melkersson–Rosenthal syndrome does not produce an epidermal phenotype." (PMID 32843345, 2020).
Sepsis (2 papers, 2013 to 2025). Sepsis is defined as life-threatening organ dysfunction caused by a dysregulated host response to infection. "Gene expression of fatty acid uptake transporters Cd36 (Cd36) and Fatp1 (Slc27a1) increased with sepsis and stayed elevated during prolonged sepsis (2.2)." (PMID 39821755, 2025).
AIDS (1 paper, 2015). A syndrome resulting from the acquired deficiency of cellular immunity caused by the human immunodeficiency virus (HIV). "The SLC27A1 gene product is involved in the translocation of long chain fatty acids across the plasma membrane, which is relevant since the free fatty acid concentration is increased in HIV/AIDS patients." (PMID 25961023, 2015).
glioblastoma (1 paper, 2023). The most malignant astrocytic tumor (WHO grade IV). "The expression of SLC27A1 was reduced in the tumor core of female glioblastoma patients compared to the enhancing tumor region (p = 0.03) and peritumoral area (p = 0.0002)." (PMID 37239243, 2023). "In glioblastoma tumors, specifically in the tumor core, women exhibit lower expression of SLC27A1 and SLC27A3, but higher expression of SLC27A5 than men." (PMID 37239243, 2023). "Additionally, the expression of SLC27A1 in the tumor core of female glioblastoma patients was lower than in male patients (p = 0.000003)." (PMID 37239243, 2023). "In addition, a positive correlation was found between the expression of SLC27A1 and SLC27A3 in the glioblastoma tumor and between the expression of SLC27A1 and SLC27A4 in the tumor core." (PMID 37239243, 2023). "According to one available study, obese women have lower expression of SLC27A1 in muscle tissue compared to lean women, which may explain the negative correlation between SLC27A1 expression and BMI and weight in the enhancing tumor region of glioblastoma tumors and the peritumoral area in women." (PMID 37239243, 2023). "We have demonstrated a positive correlation between the expression of SLC27A1 and SLC27A3 and the expression of ELOVL6 in both the glioblastoma tumor and the peritumoral area." (PMID 37239243, 2023). "Similarly to the analysis of all patients, male samples showed a positive correlation of SLC27A1 expression with SLC27A3, SLC27A4 with SLC27A5, SLC27A4 with SLC27A6, and SLC27A5 with SLC27A6 in the studied regions of the glioblastoma tumor." (PMID 37239243, 2023). "SLC27A1 participates in the transport of fatty acids across the BBB, indicating that in women, the uptake of fatty acids from the bloodstream by tumor core cells in glioblastoma may be less intense than in men." (PMID 37239243, 2023).
Hypercholesterolemia (1 paper, 2020). An increased concentration of cholesterol in the blood. "We also found altered DNA methylation in patients with hypercholesterolemia, in key genes associated with fatty acid transport and metabolism (hypomethylated: PPARD, PPARG, SLC27A1, SLC27A3 and SLC25A20, and hypermethylated: ANGPTL4, ACLS6, ACADM and CPT1A)." (PMID 33028190, 2020).
lipid metabolic disorders (1 paper, 2025). "Specifically, LLPK intervenes in biological processes such as lipogenesis, fatty acid oxidation, and fatty acid transport in mice livers by regulating the expression of key downstream factors of PPARα (Scd1, Acox1, Acaa1b, Slc27a1, Acsl1, and Ehhadh), thus improving lipid metabolic disorders." (PMID 40431433, 2025).
pituitary adenomas (1 paper, 2022). "In tumour tissues, mRNA sequencing showed that PTBP1 and EIF5A were significantly overexpressed in primary pituitary adenomas and SLC27A1 was significantly overexpressed in aggressive pituitary adenomas." (PMID 35836612, 2022). "Through a comprehensive analysis of the results of histological and cytological experiments, we found that the expression of SLC27A1 was significantly high in aggressive pituitary adenomas and TMZ therapy sensitive cell lines, while the expression of PTBP1 and EIF5A was significantly decreased." (PMID 35836612, 2022). "High expression of SLC27A1 and low expression of EIF5A and PTBP1 may be potential indicators to predict the progression of aggressive pituitary adenomas, and patients with high SLC27A1 subtype may be sensitive to TMZ in clinical treatments." (PMID 35836612, 2022). "After the data of the two groups were overlapped, it was found that PTBP1 and EIF5A were highly expressed in the primary pituitary adenomas and normal control pituitary tumor cells, and SLC27A1 was highly expressed in aggressive pituitary adenomas and TMZ-treated ATt20 cells." (PMID 35836612, 2022). "Also in the pituitary adenoma cell line (AtT20), SLC27A1 expression levels were suppressed by TMZ treatment." (PMID 35836612, 2022). "SLC27A1 was highly expressed in aggressive pituitary adenomas." (PMID 35836612, 2022). "In pituitary adenomas, the subsequent immunohistochemical results confirmed the differential expression of SLC27A1, PTBP1, and EIF5A genes in aggressive pituitary adenomas and primary pituitary adenomas, and the difference was statistically significant." (PMID 35836612, 2022). "In summary, our study demonstrates that the high expression of SLC27A1 and the low expressions of PTBP1 and EIF5A predict the progression of an aggressive pituitary adenoma." (PMID 35836612, 2022). "Therefore, SLC27A1, PTBP1, and EIF5A may be important molecular markers for predicting the recurrence of pituitary adenomas." (PMID 35836612, 2022).
triple-negative breast carcinoma (1 paper, 2023). An invasive breast carcinoma which is negative for expression of estrogen receptor (ER), progesterone receptor (PR), and human epidermal growth factor receptor 2 (HER2). "FATP1 inhibition appears to be a viable treatment method since it raised FATP1/SLC27A1 expression in human triple-negative breast cancer, which was associated with a significant reduction in overall survival." (PMID 38002353, 2023).